CD44 (CD44 molecule (IN blood group))
Diseases named in the same sentence as CD44 in open-access papers (continued):
Sharing a sentence is not in itself a finding about the gene and the disease.
tumor (continued). "At the acidic pH of the TME, HA is exposed, and by linking to the CD44 expressed on tumor cells and TAMs, it delivers the cytostatic intracellularly." (PMID 33800172, 2021). "The expression of CD44 in cancer cells and in CSC of several types of tumor substantiates the highly important role of CD44 in the development and progression of cancer." (PMID 33505471, 2021). "The positive rate of CD44 in tumor tissue was significantly higher in patients with performance status (PS) 2 than that of patients with PS 0-1 (85.71% vs 30%, P=0.017)." (PMID 34187156, 2021). "Some patients with a higher frequency of CD44-/CD24- tumor cells and CSCs had the highest rate of postoperative metastasis in this population." (PMID 34318746, 2021). "Recently, it has been discovered that CD44 interacts with xCT by binding to the surface of tumour cells." (PMID 34483935, 2021). "Membrane-bound P-gp was overexpressed in both HCT116 and MDA-MB-231 cell lines; co-delivery of DOX and siRNA in HA-DOPE-MDM can further increase the specificity and cytotoxicity in CD44 and P-gp overexpressed tumor cells." (PMID 35431911, 2021). "This phenomenon was found to be associated with an increase in MHC class I, PD-L1, and CD54 expressions and a reduction in CD44 levels on tumor cells." (PMID 33806296, 2021). "Compared with parental cells, tumor spheroid cells exhibited increased expression of stemness-associated genes, such as BMI1, OCT4, Nanog, and CD44." (PMID 33986804, 2021). "We evaluated the ability of spherical growth in vitro and tumour formation in vivo to clarify that HCT116CD133+CD44+ cells have TIC properties and analyzed the role of Cldn7 in these properties." (PMID 34281572, 2021). "Among eight patients expressing high CD44, three patients who expressed CD44 at a very high level in the tumor periphery showed early tumor progression within 2 months after Bev therapy at tumor recurrence." (PMID 33543833, 2021). "The transmembrane proteoglycan, CD44, is a hyaluronic acid (HA) receptor which is expressed in several healthy and tumor tissues." (PMID 34944101, 2021). "The remarkably high uptake in the spleen indicates that the spleen acted as a sink organ, which took up the bulk of the administered 89Zr-anti-CD44 before it had a chance to accumulate in the tumor tissue." (PMID 33594192, 2021). "Despite these known oncogenic and tumor–suppressing functions of CD44, this HA receptor is being explored as a therapeutic target, imaging agent and tumor marker in breast and other cancers." (PMID 34827550, 2021). "Accordingly, we found that combined inhibition of MET and FGFR in a basal B PDX resulted in a decrease in sphere-forming and CD44+CD24−/low populations, indicative of a loss of TICs and reduction in overall tumour burden." (PMID 33772015, 2021). "Hyaluronic acid prevented siRNA leakage during delivery and specifically targeted tumor cells with overexpressed CD44 membrane receptors." (PMID 34306980, 2021). "Our results demonstrated that CD44 within ER+ tumor cells interacted with SPP1, also known as osteopontin (OPN) with macrophages." (PMID 34685653, 2021). "Various studies reported a high chance of CD44 isoform transition in tumor cells, thereby developing different types of cancers by the activation of HA." (PMID 35431911, 2021). "LPL, as a unique downstream target of CD44 signal transduction, can activate endothelial cell-mediated angiogenesis during tumor growth." (PMID 34834495, 2021). "Among them, VEGF can regulate the angiogenesis of tumor tissues, and the hydrolysis of CD44 molecules is beneficial to the metastasis of tumor cells, thereby enhancing the ability of tumor cells to metastasize." (PMID 34422817, 2021). "In contrast, low-MW HA (LMW-HA) forms a complex cluster that binds CD44+ tumor cells and promotes cell proliferation." (PMID 34770956, 2021).
tumor (continued). "The enhanced plasticity of CSCs permits the distinct CD44+/CD24- or ALDH+ CSC populations to transition between the two CSC states which best fits the conditions of the tumor microenvironment." (PMID 35127497, 2021). "They showed a strong expression of the mesenchymal marker vimentin and N-cadherin, promoting cell migration and metastasis as well as the HNSCC tumor stem cell marker CD44 and overexpression of the oncogenic transcription factor Snai1." (PMID 34884892, 2021). "Our results showed that zotarolimus and zotarolimus combined with 5-FU largely reduced the presence of TGF-β and CD44 in tumor immunostaining." (PMID 33925400, 2021). "Our qRT-PCR results showed that circFAM73A increased the mRNA levels of HMGA2 and CD44 in xenograft tumor samples, an effect that was reversed by HMGA2 depletion." (PMID 33731207, 2021). "MiR-221 is mainly expressed in the EpCAM+/CD44+ population and represents a required component of the tumor growth in vivo." (PMID 33562604, 2021). "We further demonstrated that CD44 engagement by GPNMB activates in tumor cells the expression of several factors, including chemokines, e.g.: CXCL1, CXCL2, CCL2, CCL5, CCL7, cytokines: IL-6, IL-11, IL-33, and the IL-33 receptor: IL-1RL1, also named ST2." (PMID 34583655, 2021). "We evaluated the cluster formation efficiency of sorted PDX tumor cells with different CD44 and EGFR expression." (PMID 33995681, 2021). "A comprehensive examination of these reports suggests that CD44 is an appropriate marker for uterine mesenchymal tumor stem cells." (PMID 34563053, 2021). "The electrostatically complexed DOX@aHA-DMA0.60/Fe NPs were selectively internalized to MDA-MB-231 tumor cells via CD44-mediated endocytosis." (PMID 34200716, 2021). "Due to the limited number of available murine monoclonal antibodies against syngeneic tumours, CD44, a cancer stem cell marker, was initially used as a tumour target." (PMID 34332294, 2021). "These advantages enable accurate and efficient drug release in the acidic tumor microenvironment with high CD44 expression." (PMID 35053199, 2021). "CD44 has been reported to promote tumor progression, migration, and invasion by interacting with different proteins." (PMID 34439211, 2021). "Several authors have identified the expression of CD44 and its isoforms in tumor tissue from OST patients, which has been mentioned as a key factor in metastasis development and drug resistance." (PMID 34885185, 2021). "When surface mPEG linked with hydrazone bonds was degraded by the acidic TME, the exposed o-HA block targeted the tumour cells via its affinity for CD44." (PMID 33632232, 2021). "We also found GSC stemness-related genes, SOX2 and ID1, and MES subtype-related genes, THBS1 and CD44, enriched in the core of the tumours, together with higher TRIM28 expression." (PMID 34500575, 2021). "To find any association of IFN signaling in tumor cells with mesenchymal phenotypes, we chose five well-established signature genes of the mesenchymal phenotype: CHI3L1, CD44, SERPINE1, TNC, and TIMP1." (PMID 34771447, 2021). "Decreased cholesterol results in disordered CD44 localization, raft-dependent CD44 shedding, and the suppression of tumor cell migration." (PMID 33628817, 2021). "Our results also found the risk score based on a 5-mRNA signature was significantly associated with tumor mutational burden (TMB) and tumor stem cell markers (CD20, CD38, ABCB5, CD44, etc.)." (PMID 34805163, 2021). "In WT mice, tumor growth resulted in an expansion of EM CD8 T cells (CD44+CD62L−) in the lymph nodes at day 13 post-tumor cell challenge." (PMID 34912335, 2021). "Hyaluronic acid (HA) has been implemented for chemo and photothermal therapy to target tumour cells overexpressing the CD44+ receptor." (PMID 35011272, 2021). "CD44 was shown to be extensively expressed in the colonic stem cell niche located in the crypt base of normal or tumor colonic cells." (PMID 33819194, 2021).
tumor (continued). "Upon analysis of the TCGA-GBM dataset we observed a significant upregulation of both CD133 and CD44 in GBM patient tumours compared to non-tumour tissue." (PMID 34066147, 2021). "Mounting evidence has revealed CD44 promotes tumor metastasis and contributes to therapeutic resistance." (PMID 33661757, 2021). "CD44 is a surface glycoprotein and common CSC marker in several human tumor entities whose high expression was associated with a negative prognosis in oral cancer." (PMID 34287293, 2021). "Expression of CD44 significantly correlated with the localization of the neoplasm (parotid vs. submandibular gland; p = 0.050), a larger tumour size (T1-2 vs. T3-4; p = 0.006), positive N-category (p = 0.023), and advanced UICC stage III-IV (p = 0.002)." (PMID 33009929, 2021). "The invasiveness gene signature (IGS) was generated through comparison of the gene expression profiles of CD44+ CD24−/low tumor‐initiating cells and normal breast epithelium." (PMID 33932112, 2021). "The magnetic fluid hyperthermia generated by the anti-CD44-functionalized SPIONPs in an alternating magnetic fluid (AMF) appreciably reduced the CSC subpopulation of tumor cells in a head and neck squamous cell carcinoma model." (PMID 34361141, 2021). "As an example, HMW–HA stimulates tumor–suppressive Hippo signaling by clustering CD44, which recruits polarity–regulating kinase (PAR1b) to the intracellular domain of CD44 and leads to activation of Hippo signaling." (PMID 34827550, 2021). "HA along with its receptor, CD44, upregulates tumor cell proliferation and survival by activating intracellular signaling." (PMID 33958632, 2021). "Numerous reports have demonstrated that CD44 is located in lipid rafts and contributed to tumor progression." (PMID 33628817, 2021). "The CD44 marker expressed on skin-infiltrating tumor cells and CD44 soluble in the plasma reveal the severity of ATLL." (PMID 35432798, 2021). "Of note, tumor cells derived from basal-like or triple-negative breast cancers are enriched in CD44+/CD24−/low subpopulations." (PMID 33649296, 2021). "Dot plot analysis confirmed that anti-PD-1 increased the ratio of CD8+ CD44+ PD1+ TOX+ TIM-3low TILs (cluster 2) relative to tumor volume and that this increase was blocked by the presence of HCQ or HCQ/AZ." (PMID 34181666, 2021). "Numerous targeted nanodrug delivery systems have been designed to deliver chemotherapeutic drugs to tumor sites by targeting CD44 and other receptors." (PMID 34834387, 2021). "The degree of CD44 expression in the tumor periphery was evaluated by the ratio of the mRNA expression in the tumor periphery to that in the tumor core (P/C ratio)." (PMID 33543833, 2021). "The morphological changes induced by CD44 expression also affected the tumor-initiating capabilities of the tumor cells." (PMID 34579762, 2021). "We confirmed that the primary cells were epithelial-derived cells expressing pan-keratin, and tumor cells exhibited stemness expressing tumor marker CD44." (PMID 34778255, 2021). "The tumor suppression effect of XAV939 on CD44+CD133+-mediated tumorigenesis was examined in a NSG mouse xenograft model." (PMID 33994850, 2021). "MMP-9 can also activate TGF-ß in a functional complex with CD44 on the surface of keratinocytes and selected tumor cells." (PMID 33807594, 2021). "We first examined the CD44 mRNA expression in the canine tumours and the normal tissues surrounding the tumours by semi‐quantitative RT‐PCR." (PMID 33210459, 2021). "Cells with high expression of CD44 have drug resistance and high tumor-seeding ability through EMT, while ECAD genes are suppressed downstream to maintain EMT." (PMID 35008821, 2021). "IPA analysis for the top upstream regulators of gene expression in the non-tumour tissues G2 cluster (F6) identified CD44 as the most differentially expressed (F6D)." (PMID 34408183, 2021). "The mRNA expression of PRDX2, CD133 and CD44 in tumor tissues was significantly upregulated compared to that observed in ANTs tissues." (PMID 33819194, 2021).
tumor (continued). "CD44 is an adhesion molecule that facilitates tumor cell invasion and migration and it is concomitantly expressed with other stem-cell markers." (PMID 34884878, 2021). "Using PCa xenograft tumors, CD44+ PCa cells are shown to have stem-like cancer cell properties, and CD44+α2β1+ PCa cells are further enriched in tumor-initiating cells." (PMID 33816508, 2021). "More, CD44 is part of the molecular signature of cancer stem cells, a subpopulation of cells involved in tumor initiation, growth, and metastasis." (PMID 34066710, 2021). "All these results indicated HA mediated targeted inhibition of tumor cells via CD44-mediated endocytosis and intracellular uptake." (PMID 35431911, 2021). "Hyaluronic acid receptor Cluster of differentiation-44 (CD44) is a kind of adhesion molecule that relates to tumorigenesis and tumor metastasis." (PMID 34011362, 2021). "The role of chitosan was to target the NPs to CD44+ cells and release the drug in the slightly acidic environment of the tumor." (PMID 34361141, 2021). "HER2+ DTCs displayed similar to the analyzed primary tumor an increased CD44 expression compared to cell culture MDA-MB-453." (PMID 34070094, 2021). "Presenilin1 mediates the intramembranous cleavage of CD44 to influencing tumor cell growth and metastasis." (PMID 34781973, 2021). "An in vitro real-time imaging biodistribution and uptake study of DOX-loaded HNPs exhibited CD44-mediated tumor accumulation and uptake in the tumor cells." (PMID 35431911, 2021). "HA can bind to the over-expressed CD44 protein of tumor cells to increase targeting specificity, TPGS can inhibit the activity of P-glycoprotein (P-gp), and increase the intracellular accumulation of drugs." (PMID 33792436, 2021). "In vivo xenograft tumour formation experiments revealed that the tumorigenic ability of TAK1‐overexpressing CD44+ CD133+ GC cells was significantly greater than that of CD44+ and/or CD44‐GC cells alone." (PMID 34075691, 2021). "TDO2 overexpression was significantly associated with T classification, N classification, and M classification, tumor stage, recurrence, and basal type, and with the expression of CD44 and aldehyde dehydrogenase 1 (ALDH1) in BC." (PMID 34101386, 2021). "The upregulated expression of two stem cell markers CD44 and ALDH1 was also shown to be associated with tumor stage, recurrence, and unfavorable prognosis of BC patients." (PMID 34101386, 2021). "In the other side, OPN regulates the migration and adhesion of tumor cells by binding to its receptor CD44." (PMID 34722241, 2021). "CD44-positive cancer stem-like cells in HNSCC have the capacity for tumour initiation and long-term self-renewal." (PMID 34332294, 2021). "We previously elucidated that RT-R-TNBC displaying an enhanced capacity for tumor progression exhibited increased Notch and CD44 levels." (PMID 34502547, 2021). "Compared with HCT116CD133+CD44+shcontrol cells, HCT116CD133+CD44+shCldn7 cells exhibited a higher tumour formation rate (50% vs. 100%)." (PMID 34281572, 2021). "Clinical studies have shown an increased expression of CD44+CD24− phenotype in primary tumours after chemotherapy." (PMID 33305893, 2021). "Of these, the protein levels in the refractory PCa tissues were the highest, suggesting the presence of ALDH+CD44+CXCR4+CD24+ tumour cells in human PCa tissues." (PMID 34247196, 2021). "Administration of particles suppressed tumor growth and induced tumor cell apoptosis through targeting CD44 and the Notch-1 signaling pathway." (PMID 34198550, 2021). "SPP1_CD44 interaction was upregulated during the transition from ductal-normal cells to ductal-tumor cells but was downregulated during the malignant transition." (PMID 35087839, 2021). "HA endowed tumor-targeting properties through specifically binding to CD44 molecule, an integral membrane glycoprotein over-expressed on the surface of various tumor cells." (PMID 34834316, 2021).
tumor (continued). "Down-regulation of lncRNA TMEM161B-AS1 and/or over-expression of hsa-miR-27a-3p down-regulated the expression of FANCD2 and CD44, and inhibited the tumor growth in nude mice." (PMID 34689169, 2021). "Overall, these data showed that HCQ has a specific effect in inhibiting the ability of anti-PD-1 immunotherapy to increase the generation of CD8+ PD-1+ TCF1+ and CD8+ CD44+ PD-1+ TCF1+ progenitor TILs relative to tumor volume." (PMID 34181666, 2021). "(E) Kaplan–Meier analysis of the DFS in the testing group of TNBC patients with chemotherapy after they were stratified into ≥19.5% of CD44-/CD24- (n = 24) vs. <19.5% of CD44-/CD24- tumor cells (n = 35)." (PMID 34318746, 2021). "UMAP analysis further revealed heterogenic distribution of three liver CSC‐like markers (PROM1, EPCAM, and CD44) within tumor organoids." (PMID 34105295, 2021). "Coinciding with lncRNA KB-1980E6.3, higher levels of HIF-1α, c-Myc, and CD44 were detected in most tumor tissues, and their levels were increased in accompany with tumor stages." (PMID 33469161, 2021). "We, therefore, stained tumor-infiltrating CD8+ T cells for CD44, a marker expressed on activated antigen-experienced T cells, and observed CD44 positivity in 74.82%±5.4 of CD8+ T cells from tumors treated with triple therapy (RT+L19–IL2+anti-PD-L1)." (PMID 33688020, 2021). "By generating the heat map, two groups were identified: Group 1 contained tumour samples with high expression of BMI-1/CD44, and low expression of ALDH1/Nanog/SOX2, which correlated significantly with a higher grading (G1 vs. G2/3; p = 0.029)." (PMID 33009929, 2021). "In contrast, Abs directed against the constant domain of CD44 is likely to target other tissues in addition to tumor cells." (PMID 33594192, 2021). "The nanovector-delivered miR-34a greatly inhibited the ability of B16F10-CD44+ CSC-like cells to form spheroids in vitro as well as tumor growth in mice by attenuating CD44 expression." (PMID 33763422, 2021). "The results showed that compared with the tumor tissues in vivo, the tumor tissues have more expression of CD44 and EpCAM." (PMID 34239355, 2021). "CD44+ malignant tumor cells are in mesenchymal-1-like (MES1-like) cellular state, and CD44+ TAMs are in M2 phenotype." (PMID 35187044, 2021). "Our analysis revealed a heterogeneous population of CHCs, including those with CD44 and AR expression, which align with the phenotypes detected in both the proliferating tumor compartment and that of tumor hybrids cells." (PMID 34211050, 2021). "In this auto-regulating loop, HA content on the surface of the tumor cells and between them is regulated by CD44 molecules, which induce HAS expression." (PMID 33540535, 2021). "On the other hand, interfering with the pathway of HA/CD44 can restrict the tumor growth and metastasis." (PMID 35154001, 2021). "The cells that express CD44 were selected and bound to HA in the tumor/stroma junction, and the tumor cells invasion at the initial stage." (PMID 34770956, 2021). "Our results demonstrate that Wnt/β-catenin signaling is over-activated in the CD44+CD133+ subpopulation of Caco-2 cells, and suggest that this pathway is important for the proliferation and tumor-initiating properties of CD44+CD133+ Caco-2 cells." (PMID 33994850, 2021). "Studies have proved that the stem cell marker CD44 is correlated with tumor recurrence and treatment resistance, however, there are limited reports yet concerning on the CD44 expression and its clinical prognostic significance in SCLC patients." (PMID 34187156, 2021). "CD44+ CSCs presence at the invasive front of GC tumours indicate poor survival of patients compared to patients with no CD44 expression at invasive front and can be used as a prognosis marker." (PMID 33810350, 2021). "Further growth in situ of this initial tumor would require implantation in the host and vascularization through the overexpression of some aspecific checkpoint molecules, such as CD44, ID, LIF, HSP70, and HLA-G." (PMID 34295890, 2021).